ARID1A (AT-rich interaction domain 1A)
Diseases named in the same sentence as ARID1A in open-access papers (continued):
Sharing a sentence is not in itself a finding about the gene and the disease.
ovarian clear cell cancer (continued). "ARID1A mutations were first reported in ovarian clear cell carcinoma and subsequently described in endometrium-derived carcinomas." (PMID 33578810, 2021). "Wu and Roberts summarize that, for example, in one study, in only 30% of ovarian clear cell carcinomas with ARID1A mutations were both alleles affected by mutations." (PMID 34200508, 2021). "Mutations in ARID1A gene occur in a variety of tumors: gastric, endometrial, and clear cell ovarian cancers." (PMID 33608032, 2021). "Cyclin-E1 (CCNE1) is found as a potential therapeutic target for ARID1A-mutated ovarian clear cell carcinoma through synthetic lethality." (PMID 34680987, 2021). "While ARID1A null mice are inviable, conditional knockout of ARID1A in concert with activating mutations of PIK3CA promotes growth of tumors resembling ovarian clear cell carcinoma." (PMID 34731603, 2021). "ARID1A is now known to have the highest mutation incidence, up to 46–57%, in ovarian clear cell carcinoma." (PMID 34804958, 2021). "The frequency of ARID1A loss increases in certain cancer types, such as clear cell ovarian carcinoma where ARID1A protein is lost in about 50% of cases." (PMID 33826602, 2021). "All mutations in endometrioid carcinomas were nonsense or insertion/deletion mutations, and there was 73% and 50% of ovarian clear-cell carcinoma and endometrioid carcinoma, respectively, with an ARID1A mutation showed a loss of ARID1A expression." (PMID 33344089, 2020). "The silencing of the ARID1B gene in a ARID1A-mutated ovarian clear cell carcinoma line destabilized SWI/SNF and impaired the proliferation of the cells." (PMID 32245111, 2020). "Among the SWI/SNF subunits, ARID1A is the most frequently mutated gene, detected in 40% to 67% of clear-cell ovarian cancers." (PMID 32679669, 2020). "The ARID1A (BAF250a) subunit is mutated in approximately 50% of ovarian clear cell carcinomas (OCCC) and 30% of ovarian endometrioid carcinomas (OEC)." (PMID 32649682, 2020). "We demonstrated that ARID1A protein expression was retained in all ovarian endometriosis samples and a small portion of ovarian clear cell carcinoma samples harboring ARID1A loss-of-function mutations." (PMID 32868822, 2020). "ARID1A mutations and loss of its expression were observed in ovarian clear cell cancer, endometrioid cancer, breast cancer, Burkitt lymphoma, and lung cancer." (PMID 32245111, 2020). "Most ARID1A mutations are inactivating truncating mutations —e.g., 63% of ARID1A gene alterations in urothelial carcinomas or over 90% of ARID1A mutations in ovarian clear cell carcinoma." (PMID 33227989, 2020). "Other components of the SWI/SNF complex, such as ARID1A, are highly mutated in several cancer types, but rarely altered in ccRCC (e.g., ARID1A is mutated in 49% of ovarian clear cell carcinomas, 39% of endometrial cancers, and only in 3% of ccRCC tumors)." (PMID 31861590, 2019). "ARID1A inactivation in human ovarian clear cell carcinoma cell line (RMG-I) causes telomere damage that can be rescued by STAG1 expression." (PMID 31731647, 2019). "In fact, 46% of ovarian clear cell carcinomas and 30% of ovarian endometrioid carcinomas have ARID1A mutations." (PMID 30176911, 2018). "High rates of ARID1A mutations were observed in 46–57% of ovarian clear cell carcinomas, 30% of ovarian endometrioid carcinomas and 40% of uterine endometrioid carcinomas." (PMID 29451900, 2018). "ARID1A is a tumor suppressor gene that is frequently mutated (46%) in ovarian clear cell carcinomas (OCCC)." (PMID 29890703, 2018).
ovarian clear cell cancer (continued). "Using the largest OCCC cell line panel established to date, we show here that BRD2 inhibition is predominantly lethal in ARID1A mutated ovarian clear cell cancer cells." (PMID 29760405, 2018). "The pro-tumor role for SWI/SNF defined is distinct from its role as a tumor suppressor in other cancers, including common ARID1A loss-of-function mutations in ovarian clear cell carcinoma." (PMID 30036377, 2018). "In some cancer types, mutations are found predominantly in one specific subunit, e.g. ARID1A mutations in ovarian clear cell carcinoma, suggesting likely tissue and tumor-type specific functionality of SWI/SNF complexes." (PMID 29515757, 2018). "To search for a rational approach to target ovarian clear cell cancers with ARID1A mutations, we performed kinome-centered lethality screens in a large panel of ovarian clear cell carcinoma cell lines." (PMID 29760405, 2018). "For the study of genetically engineered mouse models, fortunately, both endometrioid and clear cell ovarian cancer have high frequency mutations in only a handful of genes: ARID1A, PIK3CA, CTNNB1, PTEN, and KRAS." (PMID 30087267, 2018). "That some cancer types exhibit clear predilections for specific mutated subunits (like ARID1A in ovarian clear cell carcinoma) suggests that SWI/SNF has distinct functions in different normal tissues and derived cancers." (PMID 29515757, 2018). "ARID1A has commonly been found mutated in gastric cancer, ovarian clear cell carcinoma, hepatocellular carcinoma, and pancreatic cancer." (PMID 28106782, 2017). "In a complementary experiment, expression of wild-type ARID1A in an ovarian clear cell carcinoma cell line containing mutated ARID1A, OVISE, affected the mevalonate pathway in a reciprocal manner." (PMID 27654507, 2016). "Somatic mutations in the ARID1A tumor-suppressor gene have been frequently identified in ovarian clear cell carcinoma (CCC) cases." (PMID 27340867, 2016). "Subsequently, we found that loss of ARID1A was associated with increased oxidative stress in vitro and in ovarian clear cell carcinoma patient samples." (PMID 27486766, 2016). "Originally, ARID1A loss was known to be an early cancer promoting event in endometriosis leading to ovarian clear cell carcinoma." (PMID 26524630, 2015). "ARID1A mutations leading to loss of the protein expression have been found in 46% of ovarian clear-cell carcinomas and 30% of endometrioid ovarian carcinomas." (PMID 26378916, 2015). "Nearly 50% of clear cell ovarian carcinomas were found to harbor ARID1A mutations resulting in loss of its encoded protein, BAF250a, a subunit of the SWI-SNF chromatin remodeling complex." (PMID 27231561, 2015). "ARID1A was mutated in 46% of ovarian clear-cell carcinomas and 30% of endometrioid ovarian carcinomas." (PMID 26378916, 2015). "They revealed the mutation of ARID1A, which codes BAF250a protein, in about half of ovarian clear cell carcinomas, and PBRM1, which codes BAF180, in approximately 40% of renal cell carcinomas." (PMID 23229642, 2013). "ARID1A mutations have been reported to be frequent in ovarian clear cell carcinomas and mutations in genes coding for it and for other components of chromatin remodeling complexes have recently been demonstrated in a wide variety of tumors." (PMID 23650517, 2013). "Of 119 ovarian clear cell carcinomas and 33 endometrioid carcinomas, ARID1A mutations were present in 55 (46%) and 10 (30%) cases, respectively." (PMID 23466883, 2013). "For example, ARID1A gene mutations result in the low protein expression in ovarian clear cell carcinoma (with mutation rate ∼50%); however, in pancreatic cancer, frequent copy number loss (47%) is the main cause." (PMID 23349767, 2013).
ovarian clear cell cancer (continued). "Mutations in the chromatin remodeling gene ARID1A have recently been identified in the majority of ovarian clear cell carcinomas (OCCCs)." (PMID 22009941, 2012). "Recently, ARID1A mutations and loss of BAF250a protein have been found to correlate strongly with the ovarian clear-cell carcinoma and uterine low-grade endometrioid carcinoma." (PMID 22808142, 2012). "In ovarian clear cell carcinoma, it is reported that ARID1A mutation is significantly associated with ARID1A immunoreactivity." (PMID 22808142, 2012). "Published in September 2010, two crucial studies showed that mutations in the ARID1a were found in roughly half of clear cell ovarian cancers tested." (PMID 21577260, 2011). "They demonstrated that the loss of the BAF250a protein was correlated strongly with the ovarian clear-cell carcinoma and endometrioid carcinoma subtypes and the presence of ARID1A mutations." (PMID 21789283, 2011). "Recent genome-wide analysis has demonstrated that somatic mutations in ARID1A (BAF250) are the most common molecular genetic changes in ovarian clear cell carcinoma (OCCC)." (PMID 21614196, 2010). "Interestingly, this phenomenon mirrors the findings in ovarian clear cell carcinoma, where ARID1A mutations are associated with promoter hypermethylation and transcriptional repression of downstream targets such as IRX1, TMEM101, and TRIP6." (PMID 41215803, 2025). "ARID1A is mutated in over 50% of ovarian clear cell carcinomas." (PMID 39471843, 2024). "Additionally, genome-wide analysis has also confirmed that ARID1A mutations have been detected in ovarian clear cell carcinomas." (PMID 37548940, 2024). "Additionally, ARID1A is more frequently lost in mismatch repair deficient ovarian clear cell carcinoma." (PMID 38893181, 2024). "For example, ARID1A is mutated in 46–57% of ovarian clear-cell carcinoma, 27% of gastric cancer, 17.5% of colon and rectal cancers, 16.7% of cholangiocarcinoma, 13% of hepatocellular carcinoma, 11% of colorectal adenocarcinoma, 9% of endometrial carcinoma, and 2.5% of malignant melanoma." (PMID 37175555, 2023). "Of all SWI/SNF subunit genes, BAF250A/ARID1A is the most commonly mutated gene in human cancers: the gene is mutated in a large proportion of ovarian clear cell cancers (~45%–57%), ~30% of endometrioid cancers, a small proportion of bladder cancers and other tumours." (PMID 36883311, 2023). "ARID1A mutations/deletions are documented in up to 80% of clear cell ovarian cancer (CCC), 56% of uterine endometrioid cancer (EC), 40% of endometrial carcinoma and endometroid ovarian cancer and 30% of mucinous ovarian cancer, but in 0% of high-grade serous ovarian cancer." (PMID 36890819, 2023). "ARID1A mutations are found in half of ovarian clear cell carcinoma (OCCC)." (PMID 38275587, 2023). "The findings in other cancer types, such as clear cell ovarian carcinoma, may provide valuable insights into potential treatment strategies for ARID1A‐deficient GC." (PMID 38041544, 2023). "The identification of ARID1A among the key genes mutated in clear cell ovarian cancer may offer new treatment opportunities in this orphan disease, poorly responsive to chemotherapy." (PMID 37711591, 2023). "ARID1A gene demonstrates >50% of mutation rate in ovarian clear-cell carcinomas (OCCC)." (PMID 36910637, 2023). "TERT promoter mutations, however, tend to be mutually exclusive with loss of ARID1A protein expression in ovarian clear cell carcinoma (OCCC), which suggested that tumours with ARID1A loss may have other mechanisms for the maintenance of telomere lengths." (PMID 38275587, 2023). "Moreover, ARID1A mutations often occur in tumors of specific subtypes (i.e. clear cell ovarian carcinoma), refractory to chemotherapy." (PMID 37711591, 2023). "ARID1A mutations are common in ovarian clear cell carcinoma." (PMID 36158348, 2022). "Loss of ARID1A expression was related to poor outcomes in ovarian clear cell carcinoma." (PMID 35870987, 2022).
ovarian clear cell cancer (continued). "Notably, inhibition of EZH2 has been suggested as a treatment for ARID1A-deficient ovarian clear cell carcinoma through a synthetic lethal relationship with ARID1A." (PMID 35326450, 2022). "The most common genetic mutations in ovarian clear cell carcinoma are adenine thymine-rich interactive domain 1A (ARID1A) and phosphatidylinositol 4,5-bisphosphate 3-kinase catalytic subunit alpha (PIK3CA) mutations, which have been identified in approximately 50% to 60% of cases." (PMID 34885229, 2021). "BETis lead to a reduction in the expression of multiple SWI/SNF members and may be a novel method for the treatment of ARID1A-mutated ovarian clear-cell carcinomas." (PMID 34404407, 2021). "ARID1A is mutated in more than 50% of ovarian clear-cell carcinomas." (PMID 34404407, 2021). "Previous studies showed that the somatic mutations of ovarian clear cell carcinoma (mainly in ARID1A, PIK3CA, KRAS and PPP2R1A) might be related to chromatin remodeling, cell proliferation, cell cycle checkpointing and cytoskeletal organization." (PMID 34680501, 2021). "Especially, 57% of ovarian clear-cell carcinomas, an aggressive human cancer, had ARID1A mutations." (PMID 32978257, 2020). "In the same way, small molecule inhibitors of the bromodomain and extra terminal domain (BET) family of proteins specifically inhibit proliferation of ARID1A mutated cell lines, both in vitro and in ovarian clear-cell cancer xenografts and patient-derived xenograft models." (PMID 32679669, 2020). "Additionally, we evaluated an association between ARID1A protein expression and the ARID1A mutation status in ovarian clear cell carcinomas by immunohistochemical analysis." (PMID 32868822, 2020). "Approximately half of ovarian clear cell carcinomas (OCCC) carry mutations in the SWI/SNF subunit ARID1A, while small cell carcinoma of the ovary hypercalcemic type (SCCOHT) presents with inactivating mutations of the SWI/SNF ATPase SMARCA4 alongside epigenetic silencing of the ATPase SMARCA2." (PMID 32649682, 2020). "Ovarian clear cell carcinoma (OCCC) is associated with a frequent loss in ARID1A function." (PMID 30787326, 2019). "Our data indicate that BET inhibition may represent a novel treatment strategy for a subset of ARID1A mutated ovarian clear cell carcinomas." (PMID 29760405, 2018). "Sequencing studies revealed that ARID1A is mutated in over 50% of ovarian clear cell carcinomas." (PMID 29760405, 2018). "A recent study on ovarian clear cell carcinoma has demonstrated a synthetic lethality between ARID1A mutation and targeted inhibition of enhancer of zeste homolog 2 (EZH2) methyltransferase through upregulation of PIK3IP1, which is a negative regulator of PI3K." (PMID 28106782, 2017). "Interestingly, an association between loss of ARID1A expression and chemoresistance has also been observed in clear-cell ovarian cancers." (PMID 28810143, 2017). "Recently, we also reported that loss of ARID1A expression may affect chemosensitivity in ovarian clear cell carcinoma." (PMID 23502469, 2013). "Moreover, loss of ARID1A expression is significantly correlated with chemoresistance in ovarian clear cell carcinoma, which is also associated with a poor prognosis of cancer." (PMID 22808142, 2012). "The Brg1Wap-Cre ovarian cyst and uterine tumor phenotype is also reminiscent of recent deep-sequencing efforts demonstrating consistent mutations of another SWI/SNF subunit, ARID1A/BAF250a, in ∼30% and ∼50% of human ovarian clear cell carcinomas and endometrial carcinomas, respectively." (PMID 22363625, 2012). "ARID1a mutations were also found in 24 of 42 clear cell ovarian carcinomas tested (57%)." (PMID 21577260, 2011).
ovarian clear cell cancer (continued). "Therefore, ovarian clear cell carcinomas with ARID1A deficiency may benefit from immune checkpoint blockade therapy." (PMID 34885229, 2021). "Importantly, it has been reported that, with regard to perimenopausal endometriosis, endometrioid ovarian carcinomas (ENOC) and clear cell ovarian carcinomas (CCOC) are associated with mutations of ARID1A, a tumor suppressor gene, PTEN, KRAS and -catenin (CTNNB1) genes." (PMID 30870972, 2019). "Importantly, small molecule inhibitors of the BET (bromodomain and extra terminal domain) family of proteins, to which BRD2 belongs, specifically inhibit proliferation of ARID1A mutated cell lines, both in vitro and in ovarian clear cell cancer xenografts and patient-derived xenograft models." (PMID 29760405, 2018). "Dasatinib selectively exerts cytotoxicity on ARID1A mutant ovarian clear cell carcinoma (OCCC) cells." (PMID 39779467, 2025). "Ovarian clear cell carcinoma (OCCC) is a rare and deadly gynecological cancer characterized by inactivating mutations in ARID1A, a component of the SWI/SNF chromatin-remodeling complex, that occur in up to 70% of patients." (PMID 40564930, 2025). "TOV21G carried mutations in ARID1A and PIK3CA, which are established drivers of ovarian clear cell carcinoma." (PMID 41228302, 2025). "In another mouse model, it was observed that ARID1A and PIK3CA mutations cooperated to promote the growth of clear-cell ovarian cancer." (PMID 38646168, 2024). "In ovarian clear cell carcinoma (OCCC), PIK3CA activating mutations occur concurrently with ARID1A deletion mutations, and mutations in PIK3CA are present in 46% of ARID1A deletion tumors." (PMID 39697230, 2024). "Somatic mutations in ARID1A, encoding one of the mutually exclusive DNA-binding subunits of SWI/SNF, occur in 42–67% of ovarian clear cell carcinomas (OCCC)." (PMID 39272926, 2024). "Recent studies have found frequent mutations, such as ARID1A and PIK3CA, in mucinous and clear cell ovarian cancer." (PMID 37024829, 2023). "Genomic alterations of ARID1A and PIK3CA have been detected in 30–60% of endometriosis-associated ovarian carcinomas, that is, endometrioid and clear cell ovarian carcinomas." (PMID 38201563, 2023). "ARID1A alterations are found in cancers that are common among Asians, including ovarian clear cell carcinoma, gastric cancer, and biliary tract cancer." (PMID 36573306, 2023). "On the one hand, preserved ARID1A is regarded as a prognostic marker in some tumors, e.g., for stage I/II ovarian clear cell carcinoma and endometrioid ovarian cancers." (PMID 37627124, 2023). "AT-rich interactive domain-containing protein 1A (ARID1A), which encodes a component of the SWI/SNF chromatin-remodeling complex, is mutated in ∼57% of ovarian clear cell carcinomas (OCCCs)." (PMID 37238613, 2023). "LncRNA MEG3 sponges miR-6088, targeting SMARCB1, and thus acts as the tumor-suppressor in glioma cells, whereas lncRNA GAS5 inhibited the cell viability and invasion of ovarian clear cell carcinoma through the activation of ARID1A by sponging miR-31-5p." (PMID 37175555, 2023). "Recent studies reported an association between ARID1A mutations and high TMB status in various types of cancer, including colorectal cancer, ovarian clear cell carcinoma (OCCC), gastroesophageal cancer, non-small cell lung cancer, and endometrial cancer." (PMID 36831552, 2023). "Recently, it has been described that ARID1A is able to transcriptionally repress histone deacetylase 6 (HDAC6) in ovarian clear cell carcinoma (OCCC); and when loss of ARID1A expression occurs, suppression of HDAC6 is relieved." (PMID 35167193, 2022). "Based on the previous publications, the highest variation rate of ARID1A in ovarian clear cell carcinoma, which is as high as 46–57%." (PMID 35421925, 2022). "AT-rich interactive domain-containing protein 1A (ARID1A), an SWI/SNF component, was shown to be mutated in more than 50% of ovarian clear cell carcinomas (OCCCs)." (PMID 36076996, 2022).